Y_RNA (Y RNA )
Gene: Miscellaneous RNA gene on chromosome 12 (127,619,336 to 127,619,447, reverse strand). Ensembl gene ENSG00000199584.
Homologues: Orthologues: chimpanzee Y_RNA (98% identical), macaque Y_RNA (94% identical). Paralogues in human: Y_RNA (86% identical), RNY1P5 (84% identical), Y_RNA (84% identical), Y_RNA (83% identical), Y_RNA (82% identical), Y_RNA (81% identical), Y_RNA (80% identical), RNY1P1 (79% identical), Y_RNA (79% identical), Y_RNA (78% identical), RNY1 (77% identical), RNY1P14 (77% identical), and 95 more.